MCL1 (MCL1 apoptosis regulator, BCL2 family member)
Diseases named in the same sentence as MCL1 in open-access papers (continued):
Sharing a sentence is not in itself a finding about the gene and the disease.
breast carcinoma (continued). "Using genetic methods, we have previously shown that MCL-1 is required for tumour development in a mouse model of breast cancer and a number of groups have shown the importance of MCL-1 for breast cancer cell line survival in vitro through genetic and pharmaceutical targeting." (PMID 33785871, 2021). "For example, a recent study indicated that a Syk inhibitor could sensitise TRAIL-induced apoptosis by downregulating Mcl-1 in breast cancer cells." (PMID 32093123, 2020). "This revealed a previously unappreciated interaction between MARCH5 and MCL1 inhibitors, with potential utility to derive predictive models of MCL1 inhibitor response across multiple cancer types, and particularly in solid tumours such as breast carcinomas." (PMID 32627965, 2020). "In addition to other members, decreased BAX/BCL-2 ratio and elevated MCL-1 expression were reported to be closely related with PTX resistance in breast cancer." (PMID 32547883, 2020). "MCL-1 may represent a potent target to treat breast tumors in particular, since Her2-amplified or chemotherapy-treated TNBC breast cancers are probably prone to MCL-1 dependence." (PMID 32722518, 2020). "Moreover, our team showed that CAFs protect luminal breast cancer cells from apoptosis by upregulating the anti-apoptotic MCL-1 in cancer cells via a paracrine IL-6 signaling, which triggers ERK phosphorylation." (PMID 33080792, 2020). "Finally, in vitro cell viability experiments have indicated effective interactions between Cu (II) dendrimers and pro-apoptotic siRNAs: Mcl-1 and Bcl-2 in breast cancer cells." (PMID 32748821, 2020). "Similarly, the present research showed that the knockdown of ERK in breast cancer cells decreased Mcl-1 expression and increased the induction of apoptosis in breast cancer cells." (PMID 31404252, 2019). "Some studies have shown that resistance occurs via up-regulation of pro-survival members of the BCL-2 family, including BCL-2 and MCL-1, although BCL-2 is commonly associated with ER positivity and better prognosis in breast cancer, being a favorable prognostic marker." (PMID 30720718, 2019). "Importantly, we have tested the Mcl-1 selective inhibitor VU661013 in ER+ breast cancer cells, finding that Mcl-1 inhibition increases apoptosis and decreases tumor cell death, particularly when used in combination with ABT-263." (PMID 31595181, 2019). "Importantly, MCL-1 expression in bCAFs was confirmed by immunostaining of 20 formalin fixed luminal breast cancer samples." (PMID 30631150, 2019). "There is now good evidence suggesting that MCL-1 mediates basal breast cancer cell survival and therapeutic resistance, with several studies showing the importance of this protein in therapeutic resistance where its suppression or antagonism is important for re-sensitization to cytotoxic therapies." (PMID 30720718, 2019). "Interestingly, VU661013-treated ER+ breast cancer cells upregulated Mcl-1 protein levels, as shown by western analysis, although PLA confirmed that Mcl-1 interactions with Bim remained suppressed by VU661013." (PMID 31595181, 2019). "Our study widens the therapeutic indications of MCL-1 inhibitors to luminal breast cancers." (PMID 30631150, 2019). "A recent study examining PIK3CA-mutant breast cancers showed that heightened PI3K-mTOR signaling is a key driver of Mcl-1 overexpression in these tumor cells, and that PI3K/mTOR inhibition impaired Mcl-1 expression, increasing PIK3CA-mutant cell sensitivity to ABT-263." (PMID 31595181, 2019). "Additionally, MCL-1 complexes with MULE are only transiently found in breast cancer cells and this has been shown to play a significant role in increased MCL-1 protein stability." (PMID 30720718, 2019).
breast carcinoma (continued). "Furthermore, MCL1 was noted to be frequently amplified in endocrine therapy resistant breast cancer, and prostate cancer." (PMID 31370269, 2019). "The induction of MAPK signaling through EGF stimulation up-regulated Mcl-1 in breast cancer cells." (PMID 31404252, 2019). "Moreover, OTUD1 also increases MCL1 protein levels in the MCF7 breast cancer cell line and the Huh7 liver cancer cell line." (PMID 31467488, 2019). "Moreover, downregulation of FBXW7 in MDA-MB-468R breast cancer cell induced resistance to the drug paclitaxel by the accumulation of its substrates myeloid cell leukemia 1 (MCL-1) and polo-like kinase 1 (PLK1)." (PMID 30791487, 2019). "Notably, miR-193b functions as a tumor suppressor in melanoma, pancreatic cancer, breast cancer, and prostate cancer by suppressing targets including uPA, Mcl1, and cyclin D1." (PMID 32038504, 2019). "This may suggest that, in ER+ breast cancers, Mcl-1 plays a dominant role among Bcl-2 family members under conditions in which an imbalance of pro- and anti-apoptotic factors threaten cell survival." (PMID 31595181, 2019). "Importantly, Mcl-1 is a key survival factor used by several cancers to promote cell survival upon inhibition of Bcl-2 and Bcl-xL, including ER+ breast cancers." (PMID 31595181, 2019). "Interestingly, western analysis did not reveal a pattern specifically implicating either Bcl-2 or Bcl-xL inhibition as a main driver of Mcl-1 upregulation across all three ER+ breast cancer cell lines tested." (PMID 31595181, 2019). "A growing body of data suggests that Mcl-1 may play a strategic role in ERα+ breast cancers, a breast cancer subtype that expresses Bcl-2, Bcl-xL and Mcl-1." (PMID 31595181, 2019). "We find that MCL-1 is important in breast cancer stem cells and targeting MCL-1 could be particularly important in the context of treatment resistance and recurrence." (PMID 30405205, 2018). "We have shown that high levels of MCL-1 predict poor prognosis in breast cancer." (PMID 30405205, 2018). "These conflicting reports, in addition to a lack of studies observing the role of other anti-apoptotic factors in ERα+ breast cancer resistance, led us to further explore the role of Bcl-2, as well as Bcl-xL and Mcl-1, in response of ERα+ breast cancers to endocrine inhibition." (PMID 29343814, 2018). "Our findings suggest this resistance may not necessarily be acquired in response to therapy, but in many cases may be innate, due to the required presence of high MCL-1 in breast cancer development." (PMID 29339815, 2018). "These interesting hypotheses will require further investigation, as MCL1 gene regulation is likely a key deciding element governing tumor cell death in therapeutically treated ERα+ breast cancers." (PMID 29343814, 2018). "Overall, these studies demonstrate ERα+ breast cancers treated with standard of care endocrine inhibitors may induce Mcl-1 expression and/or activity, which could represent a potential dynamic biomarker of sensitivity to Mcl-1 inhibition." (PMID 29343814, 2018). "MCL1 mRNA is higher in Basal (including Claudin-low (CL)) breast cancers relative to other subtypes and we reasoned that MCL-1 may have differential prognostic significance in certain subtypes of breast cancer." (PMID 29339815, 2018). "The associations between high MCL-1 and poor outcome, along with the observed frequent amplification of MCL1 in breast cancer may reflect a requirement for MCL-1 in the oncogenic process as has been observed in haematopoietic cancers." (PMID 29339815, 2018). "Further, inhibition of Mcl-1 in tumors that are primed by endocrine inhibition may be viable strategy to increase tumor cell killing and breast cancer patient survival." (PMID 29343814, 2018). "We determined whether miR-296-5p expression correlated with BOK and Mcl-1 expression levels in breast cancer patients." (PMID 29156771, 2017).
breast carcinoma (continued). "Indeed, ectopic expression of BOK induced Mcl-1 expression, while silencing of Mcl-1 resulted in reduced expression of BOK in breast cancer cells." (PMID 29156771, 2017). "Next, we addressed the clinical significance of miR-296-5p and Mcl-1 in breast cancer patients." (PMID 29156771, 2017). "Indeed, levels of several pro-survival proteins were found to be elevated when breast cancer cells were depleted for both Mcl-1 and BOK compared to silencing of either of them alone." (PMID 29156771, 2017). "It is possible that differential regulation of BOK and Mcl-1 by miR-296-5p may determine whether pro- or anti-apoptotic functions prevail and accordingly affect the survival of breast cancer patients." (PMID 29156771, 2017). "In addition to MCL-1 dysregulation, breast cancer cell lines of the growth phenotype expressed lower levels of the pro-apoptotic protein BIM." (PMID 28446242, 2017). "Next, we assessed whether the compensatory effects of BOK and Mcl-1 silencing on breast cancer growth has similar effect on apoptosis." (PMID 29156771, 2017). "MCL1 has been shown to upregulate ERBB2 expression in breast cancer cells." (PMID 28415602, 2017). "MCL1 is frequently amplified in numerous cancers, such as breast cancer, AML and NSCLC." (PMID 29072681, 2017). "Recently it has been reported that breast cancer cells rely on MCL-1 for survival." (PMID 29187162, 2017). "Interestingly, miR-296-5p also regulates the expression of anti-apoptotic protein myeloid cell leukemia 1 (Mcl-1), which is highly expressed in breast cancers." (PMID 29156771, 2017). "Furthermore, exposure of SQ20B cells to ABT-737, alone or in combination with radiation, was in contrast found to up-regulate Mcl-1 expression, a result that was previously reported in lymphoma and breast cancer cells." (PMID 26934442, 2016). "miR-363 sensitizes cisplatin-induced apoptosis targeting in Mcl-1 in breast cancer." (PMID 32309578, 2016). "Given several studies showing an important role for MCL1 in the resistance of breast cancer cells to apoptosis, and other reports that MCL1 expression is suppressed at the level of transcriptional elongation by CDK9i in a range of cell types, we decided to explore its role in the present system." (PMID 26812885, 2016). "To examine whether targeting MCL-1 may provide an effective treatment for breast cancer, we constructed inducible models of BIMs2A expression (a specific MCL-1 inhibitor) in MDA-MB-468 (MDA-MB-468-2A) and MDA-MB-231 (MDA-MB-231-2A) cells." (PMID 27931239, 2016). "MCL-1 also has been shown to confer the survival of breast cancer cells in vitro." (PMID 27931239, 2016). "To further investigate whether FBXW7 expression correlated with its substrates in breast cancer tissues, we decided to study the protein levels of Cyclin E, MCL1, AURKA and PLK1 in these samples." (PMID 27409838, 2016). "Finally, we observed that APA exerts antiproliferative effects through inactivation of Akt and suppression of BCL-2 and MCL-1 in primary cancer cells from breast cancer patients." (PMID 26943775, 2016). "In this study, we found that MCL-1 was significantly overexpressed in MCF-7/DOXR cells, suggesting that the MCL-1 might be essential for doxorubicin resistance in breast cancer." (PMID 26526790, 2015). "We assessed the effect of miR-101 and MCL-1 on breast cancer growth both in vitro and in vivo." (PMID 26036638, 2015). "Additionally, expression of Mcl-1 in human breast cancer samples correlates with high tumor grade and a dramatic decrease in patient survival regardless of subtype." (PMID 25784482, 2015). "MCL1 is also genetically amplified in 9% of luminal B breast cancers and 54% of TNBCs after treatment with neoadjuvant chemotherapies, suggesting that Mcl-1 may represent a more desirable target over Bcl-2/Bcl-xL in some breast cancers." (PMID 25784482, 2015).
breast carcinoma (continued). "Similarly, SRSF1 expression promotes inclusion of exon 2 of the BH3 domain-containing gene MCL-1 (myeloid cell leukemia-1) giving rise to the antiapoptotic MCL-1L isoform in both breast cancer and choriocarcinoma cells." (PMID 26273603, 2015). "Indirect evidence that targeting of Mcl-1 in combination with lapitinib could sensitize breast cancer cells to radiotherapies was gained using the pan-BCL2 inhibitor obatoclax, a BH3-mimetic that displaces BIM from all anti-apoptotic BCL2 family members." (PMID 25784482, 2015). "Furthermore, our study provided new insight into the molecular basis of doxorubicin resistance; that is, miR-193b sensitizes breast cancer cells to doxorubicin by targeting myeloid cell leukemia-1 (MCL-1)." (PMID 26526790, 2015). "More importantly, we found doxorubicin-induced apoptosis was inhibited in MCF-7/DOXR cells cotransfected with MCL-1 expression vector and miR-193b mimic, indicating that MCL-1 plays a pivotal role in mediating miR-193b-modulated doxorubicin resistance in human breast cancer." (PMID 26526790, 2015). "This review will focus on the role of Bcl-2 family proteins in normal breast development, breast tumorigenesis and acquired resistance to breast cancer treatment strategies, while highlighting Mcl-1 as a promising target to improve breast cancer tumor cell killing." (PMID 25784482, 2015). "These oncogenic signaling pathways rapidly increase Mcl-1 to promote cell survival, suggesting that Mcl-1 may be an important mediator of apoptotic escape and therapeutic resistance in many cancers, including breast cancers." (PMID 25784482, 2015). "These inhibitors may provide a feasible and rapidly translatable approach to limiting Mcl-1 activity in breast cancers." (PMID 25784482, 2015). "The aim of this study was to investigate whether miR-193b mediated the resistance of breast cancer cells to doxorubicin by targeting myeloid cell leukemia-1 (MCL-1)." (PMID 26526790, 2015). "Furthermore, most of the derivatives were cell active as demonstrated by their ability to decrease the levels of Mcl-1, induce apoptosis and inhibit tumor cell growth of human breast cancer cells." (PMID 25076060, 2014). "This investigation may be particularly important because several mediators of breast cancer signaling and tumorigenicity, in addition to Mcl-1, are regulated by USP9X." (PMID 25606592, 2014). "Future studies regarding the role of estrogen in mediating apoptosis will help determine whether Mcl-1 is a valid molecular target for breast cancer therapy." (PMID 24971890, 2014). "In addition, enhanced expression of MCL1 is observed in a wide range of tumors, including hepatocellular carcinoma, breast cancer, etc." (PMID 25386925, 2014). "In breast cancer, it was been previously shown that epidermal growth factor receptors up-regulate Mcl-1 but the role of estrogen in increasing Mcl-1 expression was unknown." (PMID 24971890, 2014). "Overall, this suggests that targeting Mcl-1 may provide a mechanism for overcoming drug resistance in breast cancer patients." (PMID 24971890, 2014). "Our data are also in agreement with recent studies showing that inhibition of S6K1 with either PF4708671 (a selective inhibitor of S6K1) or specific siRNA led to a marked decrease of Mcl-1, enhancing tamoxifen- or glucose deprivation-induced apoptosis in breast cancer cell." (PMID 24566141, 2014). "As reported at the molecular levels p-ERK1/2 accelerates Bik degradation and promotes anti-apoptotic Bcl-2 homolog expressions, in this study we discovered p-ERK1/2 expression inversely correlated with Bik and positively with Bcl-Xl and Mcl-1 in breast cancer patients’ tissues." (PMID 24637719, 2014). "However, reducing the threshold to MCL1 copy number of ≥3 would allow for ∼8% of breast cancers to be eligible." (PMID 25289887, 2014). "ERα-mediated overexpression of Mcl-1 may contribute to drug resistance by providing a mechanism by which breast cancer cells can evade apoptosis." (PMID 24971890, 2014).
breast carcinoma (continued). "Our results indicate that ERα is an important regulator in maintaining Mcl-1 expression and may counteract post-translational Mcl-1 degradation, allowing for evasion of apoptosis in ERα positive breast cancer." (PMID 24971890, 2014). "As a positive control for estrogen treatment, progesterone receptor expression levels were shown to increase after estrogen treatment in MCF-7 cells This data suggests that estrogen signaling is involved in up-regulating Mcl-1 protein expression in ERα+ breast cancer cell lines." (PMID 24971890, 2014). "Thus, miR-26a impacts on cell proliferation and migration of breast cancer by regulating several carcinogenesis-related processes, including a novel mechanism involving the targeting of MCL-1." (PMID 23750239, 2013). "In addition, IHC was carried out to detect MCL-1 expression in breast cancer tissues which were used for miR-26a detected." (PMID 23750239, 2013). "Breast cancer cells often express high levels of Bcl-2, Bcl-xL, and/or Mcl-1." (PMID 22703841, 2012). "Furthermore, sensitivity of HER2-positive breast cancer cells resistant to anti-HER2 therapies are related to antiapoptotic proteins MCL1 and Survivin." (PMID 22905152, 2012). "Interestingly, this observation is supported by a recent report that shows that the co-silencing of Bcl-2, Bcl-xL, and Mcl-1 in breast cancer cell lines potently reduced mammosphere formation." (PMID 22703841, 2012). "To evaluate whether the bortezomib could also induce Mcl-1 accumulation in other cancer cells besides the cell lines used as above, we chose the human breast cancer MCF7 cell line which was purchased from ATCC." (PMID 22078414, 2011). "Our current findings may suggest that increasing 26S proteosome-mediated degradation of Mcl-1 might have therapeutic benefits in inducing apoptosis in breast cancer cells." (PMID 21730980, 2011). "We were unable to detect significant association of another known E3 ligase β-TrCP with Mcl-1 in either normal mammary epithelial or breast cancer cells (data not shown)." (PMID 21730980, 2011). "It has been shown that ERK1/2 can phosphorylate and stabilise Mcl-1 in breast cancer cells." (PMID 21730980, 2011). "To examine whether a decline in Puma could promote Mcl-1 ubiquitination and degradation, we downregulated Puma in breast cancer cell lines with Puma siRNA and examined Mcl-1–Mule complex." (PMID 21730980, 2011). "Only transient formation of the Mule–Mcl-1 complex was detected in breast cancer cells." (PMID 21730980, 2011). "We demonstrate that unstable binding of Mcl-1 with E3 ligase Mule could be one of the prominent mechanisms that increases stability of Mcl-1 in breast cancer cells." (PMID 21730980, 2011). "Compounds 4 and 5 exhibited a 12.7-fold increase in Mcl-1/Bim binding inhibition and a 27.3-fold increase in Bcl-XL/Bim binding inhibition compared to marinopyrrole A. Despite their increased anti-apoptotic Bcl-2 family inhibition, efficacy against the breast cancer cell line MDA-MB-468 was limited." (PMID 41149606, 2025). "Complete suppression of mTORC1 by RMC-6272 causes apoptosis in ER+/HER2− breast cancer cell lines, particularly in those that harbor mutations in PIK3CA or PTEN, due to inhibition of the rapamycin resistant, mTORC1 substrate 4EBP1 and reduction of the pro-survival protein MCL1." (PMID 37264081, 2023). "Furthermore, the Mcl-1 nioplex/TZ dual treatment establishes a synergistic outcome that may have the potential to treat HER2-overexpressing breast cancer." (PMID 37896184, 2023). "However, pharmacological inhibition of Bcl-2 and Bcl-xL, alone or combination, in breast cancer cells causes the induction of Mcl1 and therefore fails to inhibit tumor cell growth." (PMID 36853387, 2023).